CDC7 (cell division cycle 7)
Diseases named in the same sentence as CDC7 in open-access papers (continued):
Sharing a sentence is not in itself a finding about the gene and the disease.
triple-negative breast carcinoma (3 papers, 2015 to 2022). An invasive breast carcinoma which is negative for expression of estrogen receptor (ER), progesterone receptor (PR), and human epidermal growth factor receptor 2 (HER2).
brain tumor (2 papers, 2016 to 2022). "By using a commercial PCR array specific to known miRNAs related to different tumors of the brain and central nervous system, we determined that CDC7 inhibition leads to upregulation of hsa-miR-451a (2.34-fold) and hsa-miR-320a (1.96-fold) in U87-MG cells." (PMID 27891063, 2016). "One study found that, in a brain tumor, PGK1N promoted DNA replication in cooperation with Cdc7." (PMID 36292976, 2022).
endometrial cancer (2 papers, 2021 to 2022). Primary or metastatic malignant neoplasm involving the endometrium (mucous membrane that lines the endometrial cavity). "While there are drugs specifically targeted at CDC7, the CDC7 transcript is decreased in Blacks and thus is not a rational target for Black race-specific endometrial cancer treatment." (PMID 33920951, 2021).
Fanconi anemia (2 papers, 2017 to 2025). Fanconi anemia (FA) is a hereditary DNA repair disorder characterized by progressive pancytopenia with bone marrow failure, variable congenital malformations and predisposition to develop hematological or solid tumors. "Again, DNA repair and cell-cycle-related genes (e.g., Fanca, Brca1, Eme1, Cdc6, Cdc7, Chek1) are enriched (e.g., KEGG terms: Fanconi anemia pathway, homologous recombination, cell cycle, Base excision repair)." (PMID 28638111, 2017).
glioblastoma (2 papers, 2016 to 2020). The most malignant astrocytic tumor (WHO grade IV). "While CDC7 inhibition appears to cause selective cytotoxicity in glioblastoma cells, these results should be confirmed further in primary human astrocytes and other non-tumorigenic cells." (PMID 27891063, 2016). "After determining the IC50 value, we aimed to analyze how glioblastoma cell viability changes in response to CDC7 inhibition." (PMID 27891063, 2016). "By using real-time PCR arrays, we found that CDC7 inhibition alters the expression of several mRNAs and miRNAs in glioblastoma cells." (PMID 27891063, 2016). "Taken together, our findings suggest that CDC7 inhibition is a promising strategy for treatment of glioblastoma." (PMID 27891063, 2016). "To determine if CDC7 inhibition also suppresses cell proliferation in glioblastoma cells, we used a chemiluminescent bromodeoxyuridine (BrdU) incorporation assay." (PMID 27891063, 2016). "We provided substantial evidence that CDC7 inhibition suppresses glioblastoma growth and invasiveness." (PMID 27891063, 2016). "Here, we aimed to test the potential of CDC7 inhibition as a new strategy for glioblastoma treatment." (PMID 27891063, 2016). "In parallel, we also performed a transwell invasion assay to test the effect of CDC7 inhibition on glioblastoma cell invasion." (PMID 27891063, 2016). "Considering that the majority of these genes are classified as growth factors and receptors, it is possible that glioblastoma cells are trying to compensate the tumor suppressive effect of CDC7 inhibition by activating key genes related to cell survival." (PMID 27891063, 2016). "Taken together, these results indicate that CDC7 inhibition suppresses glioblastoma cell migration and invasion." (PMID 27891063, 2016). "Taken together, these results demonstrate that CDC7 inhibition suppresses glioblastoma cell proliferation, and induces apoptosis." (PMID 27891063, 2016). "Two glioblastoma cell lines (U87-MG and U251-MG) and a control cell line (3T3) were used to characterize the effects of CDC7 inhibition." (PMID 27891063, 2016). "In this study, we focused on multiple aspects of glioblastoma biology to understand the consequences of CDC7 inhibition in vitro." (PMID 27891063, 2016). "Our results showed that CDC7 inhibition reduces glioblastoma cell viability, suppresses cell proliferation, and triggers apoptosis in glioblastoma cell lines." (PMID 27891063, 2016). "Our next question was to determine whether CDC7 inhibition would also induce apoptosis in glioblastoma cells." (PMID 27891063, 2016). "In addition, we determined that CDC7 inhibition also suppresses glioblastoma cell migration and invasion." (PMID 27891063, 2016). "In addition, our results provide preliminary evidence that CDC7 inhibition alters the glioblastoma transcriptome by upregulating and downregulating key genes involved in different cellular pathways." (PMID 27891063, 2016). "Overall, our results indicate that CDC7 inhibition suppresses glioblastoma growth and invasiveness." (PMID 27891063, 2016). "Contrary to glioblastoma cells, CDC7 inhibition did not cause a significant increase in the level of DNA fragmentation in 3T3 cells." (PMID 27891063, 2016). "Taken together, these results suggest that CDC7 inhibition may suppress glioblastoma growth through CTSS." (PMID 27891063, 2016). "Our next goal was to identify whether CDC7 inhibition has any effect on glioblastoma cell migration and invasion." (PMID 27891063, 2016). "In addition, we found that CDC7 inhibition suppresses glioblastoma cell migration and invasion." (PMID 27891063, 2016). "Here, we report that CDC7 inhibition by PHA-767491 hydrochloride inhibits cell proliferation and induces apoptosis in glioblastoma cells." (PMID 27891063, 2016). "Notably, our results suggest that CDC7 inhibition may suppress glioblastoma growth through CTSS." (PMID 27891063, 2016).
glioblastoma (continued). "ERK and CK2α were recently found to promote DNA replication in an EGFR dependent manner in human glioblastoma cells by decreasing an ADP-dependent negative feed-back regulation acting on CDC7/ASK51." (PMID 32612138, 2020). "Overall, these findings indicate that PHA-767491 hydrochloride effectively decreases cell viability in glioblastoma cells in a time-dependent fashion, and CDC7 inhibition exerts limited effects on non-tumorigenic cells." (PMID 27891063, 2016). "In addition, CDC7 inhibition does not induce apoptotic cell death in 3T3 cells, unlike glioblastoma cells." (PMID 27891063, 2016).
osteosarcoma (2 papers, 2012 to 2023). A usually aggressive malignant bone-forming mesenchymal neoplasm, predominantly affecting adolescents and young adults. "Although Cdc7 depletion in U2OS cells (human osteosarcoma), induced vigorous cell death, the levels of the mitotic kinases did not increase." (PMID 22574151, 2012).
ameloblastoma (1 paper, 2022). The most common odontogenic tumor, arising from the epithelial component of the embryonic tooth and usually affecting the molar-ramus region of the mandible or maxilla. "The results showed a higher expression rate of CDC7 in ameloblastoma and ameloblastic fibroma compared to AOT (p=0.009 and p=0.048, respectively)." (PMID 36483932, 2022). "The higher expression of CDC7 in ameloblastoma and ameloblastic fibroma in comparison with AOT confirms the hamartomatous growth of the latter, so it can be considered as a potential diagnostic marker." (PMID 36483932, 2022). "In the limited cases of unicystic ameloblastomas, the luminal types showed a minimum level of CDC7 expression (about 1%), and in mural ameloblastoma, CDC7 was found in the epithelial cells of the invaded ameloblastic nests, similar to the solid ameloblastomas." (PMID 36483932, 2022). "In this study, 80% of tumors, including ameloblastoma, ameloblastic fibroma, and AOTs, showed very low CDC7 expression, with a mean of 7%." (PMID 36483932, 2022). "In the present study, despite the low protein expression, ameloblastoma is an invasive benign tumor, and ameloblastic fibroma showed higher CDC7 expression than AOT, which develops hamartomatous." (PMID 36483932, 2022). "The higher expression of CDC7 in ameloblastoma and ameloblastic fibroma in comparison with AOT might confirm the hamartomatous growth of the latter and can be considered as a potential diagnostic marker." (PMID 36483932, 2022). "Ameloblastoma and ameloblastic fibroma were not significantly different in CDC7 expression (p=0.6)." (PMID 36483932, 2022).
ampullary adenocarcinoma (1 paper, 2016). "Importantly, Cdc7 was found to be strongly positively correlated with the other markers, confirming that actively cycling cells have high levels of Cdc7 and that Cdc7 is a potential therapeutic target in pancreatic ductal and ampullary adenocarcinoma." (PMID 26921250, 2016).
B-cell lymphoma (1 paper, 2018). "Overexpression of CDC7 in malignant tumors correlates with tumor differentiation and poor prognosis in patients with B-cell lymphoma." (PMID 30363964, 2018).
colorectal tumour (1 paper, 2024). "The ATR, CHEK1 and CDC7 synthetic lethal effects can be replicated using small molecule inhibitors and in addition, the CDC7 dependency of colorectal tumour cell lines with reduced FBXW7 mRNA expression in the DepMap dataset was seen." (PMID 37866880, 2024).
esophageal cancer (1 paper, 2022). A primary or metastatic malignant neoplasm involving the esophagus. "CDC7 overexpression has also been implicated in chemoresistance development in esophageal cancer, with sensitivity restored via CDC7 knockout." (PMID 36970056, 2022).
Insulin resistance (1 paper, 2021). Increased resistance towards insulin, that is, diminished effectiveness of insulin in reducing blood glucose levels. "The target genes TRDMT1, ZNF418, NAT1, and CDC7 have been experimentally associated through their expression levels or through knockouts, or are used as biomarkers, for waist circumference, BMI, obesity, or insulin resistance." (PMID 33957961, 2021).
lymphoma (1 paper, 2022). A malignant (clonal) proliferation of B- lymphocytes or T- lymphocytes which involves the lymph nodes, bone marrow and/or extranodal sites. "We identified CDC7 as a key gene whose expression correlates with the degree of stemness and show CDC7-inhibitor reverse growth of human lymphoma cell lines in vitro and in a mouse xenograft model." (PMID 36426371, 2022). "CDC7 expression correlated with the degree of stemness, and CDC7-inhibitors significantly increased apoptosis (P < 0.01), the proportion of cells in G1 phase (P < 0.01), and inhibited lymphoma growth in a mice xenograft model (P = 0.04)." (PMID 36426371, 2022). "The results showed that dequalinium could target CDC7 to inhibit lymphoma proliferation and promote lymphoma apoptosis in vivo and consistent with in vitro." (PMID 36426371, 2022).
metastatic melanoma (1 paper, 2019). A melanoma that has spread from its primary site to another anatomic site. "Other previous studies also reported the overexpression of CDC7 in primary and metastatic melanoma compared to benign nevi, and was associated with lower relapse-free survival." (PMID 31578454, 2019). "Further studies are warranted to investigate the clinical effect of targeting CDC7 in metastatic melanoma." (PMID 31578454, 2019).
odontogenic cyst (1 paper, 2022). A cyst in the jaw that arises from tissues of tooth development. "In a previous study, we detected CDC7 in 3.5%–20% of the basal cells in some odontogenic cysts." (PMID 36483932, 2022). "Moreover, in a previous study, we showed an increased CDC7 expression rate in odontogenic keratocyst (OKC), which are locally aggressive odontogenic cysts, in comparison with dentigerous cysts." (PMID 36483932, 2022).
odontogenic tumors (1 paper, 2022). "The aim of this study was to evaluate the expression rate and usefulness of CDC7 in the differential diagnosis of some odontogenic tumors." (PMID 36483932, 2022). "According to the results, the expression of the CDC7 protein in odontogenic tumors is low." (PMID 36483932, 2022). "The aim of this study was to evaluate CDC7 in some odontogenic tumors." (PMID 36483932, 2022).
orthostatic hypotension (1 paper, 2022). Sudden fall of the blood pressure of at least 20/10 mm Hg when a person stands up. "Interestingly, this study also excluded patients with significant baseline hypotension, and reported rates of drug-related orthostatic hypotension of 50%, suggesting that hypotension may be a class effect of CDC7 inhibition." (PMID 36970056, 2022).
pancreatic adenocarcinoma (1 paper, 2016). "Cdc7 was significantly overexpressed in pancreatic adenocarcinoma compared to benign pancreatic tissue (median LI 34.3% vs. 1.3%; P<0.0001)." (PMID 26921250, 2016). "Following CDC7 knockdown with siRNA, pancreatic adenocarcinoma cells undergo pronounced apoptotic cell death." (PMID 26921250, 2016). "Cdc7 target validation was performed by immunoexpression profiling in a cohort of 73 patients with pancreatic adenocarcinoma including 24 controls." (PMID 26921250, 2016). "Our findings show that Cdc7 is a potent anti-cancer target in pancreatic adenocarcinoma and that Cdc7 immunoexpression levels might be used as a companion diagnostic to predict response to therapeutic siRNAs or SMIs directed against this kinase." (PMID 26921250, 2016).
prostate adenocarcinoma (1 paper, 2024). "In sum, CDC7, as a therapeutic target, can control lineage plasticity and NEtD, and its upregulation confers to acquired resistance to targeted therapies in lung and prostate adenocarcinoma." (PMID 39372390, 2024). "CDC7 inhibitor simurosertib suppresses NEtD by inducing MYC degradation in vivo and prolongs lung and prostate adenocarcinoma response to therapy." (PMID 39372390, 2024).
prostate small cell carcinoma (1 paper, 2024). A neuroendocrine carcinoma of the prostate gland with unfavorable prognosis, composed of small cells containing neurosecretory granules. "CDC7 inhibition also markedly extended response to standard cytotoxics (cisplatin, irinotecan) in lung and prostate small cell carcinoma models." (PMID 39054323, 2024).
salivary gland tumors (1 paper, 2019). "This study investigated the expression of cell division cycle-7 protein in benign and malignant salivary gland tumors and also its correlation with clinicopathologic factors." (PMID 29339028, 2019).
cancer (75 papers, 2011 to 2025). A tumor composed of atypical neoplastic, often pleomorphic cells that invade other tissues. "TAK-931 is a CDC7-selective kinase inhibitor that has anti-proliferative activity across various cancer cell lines and causes tumor growth inhibition in multiple cancer xenograft models, including human colorectal, lung, ovarian, and pancreatic cancer." (PMID 41413594, 2025). "Increased CDC7 expression has been observed in many advanced cancer and is associated with poor prognosis in ovarian and triple-negative breast cancer." (PMID 41413594, 2025). "Over‐expression of CDC7 has been reported to be associated with poor prognosis in a range of cancers, including OV." (PMID 39412086, 2024). "At the same time, we can further explore the possible mechanism of malignant tumors caused by high CDC7 expression." (PMID 33763482, 2021). "CDC7 encodes a widely expressed protein kinase implicated in cell division, cell cycle checkpoint mechanisms, and cancer progression." (PMID 30823486, 2019). "In mammalian cells, induced knockout of Cdc7 gene in mouse ES cells as well as siRNA-mediated inhibition of Cdc7 expression in cancer cells resulted in almost complete loss of Chk1 activation in response to HU or UV irradiation." (PMID 31889509, 2019). "CDC7 is a widely expressed serine/threonine kinase which is implicated in cell division, cell cycle, checkpoint and cancer progression mechanism." (PMID 30150654, 2018). "Cdc7 is a widely expressed protein kinase implicated in cell division, cell cycle checkpoint mechanisms and cancer progression." (PMID 26208856, 2015). "As apoptosis induced by CDC7 depletion in cancer cells is associated with ATR-activated p38 kinase, we examined phosphorylation/activation of p38 kinase in CDC7-silenced A549 cells, where phosphor-p38 was upregulated." (PMID 25255219, 2014). "Cdc7 inactivation in cancer cell lines causes growth arrest and cell death, while only arresting growth in normal cells." (PMID 21595939, 2011). "The checkpoint defect by the loss of Cdc7 specifically observed in cancer cells may explain cancer cell-specific cell death induction by Cdc7 inhibition, since failure to properly respond to replication stress would be directly linked to genome instability." (PMID 31889509, 2019). "Furthermore, functional studies of CDC7 in cancer cell lines have suggested that inactivation of CDC7 causes growth arrest and cell death preferentially in cancer cells while in contrast, depletion of CDC7 in normal cells led to cell cycle arrest without inducing cell death." (PMID 30823486, 2019). "Our data indicate that systemic interference with Cdc7/Cdk9 activity results in a strong suppression of the adaptive immune response and likely affects not only the adaptive response to tumors but also the ability of the immune system to react to cancer-associated opportunistic infections." (PMID 31402912, 2019).